PSMD5 (proteasome 26S subunit, non-ATPase 5)
Description:
Acts as a chaperone during the assembly of the 26S proteasome, specifically of the base subcomplex of the PA700/19S regulatory complex (RC). In the initial step of the base subcomplex assembly is part of an intermediate PSMD5:PSMC2:PSMC1:PSMD2 module which probably assembles with a PSMD10:PSMC4:PSMC5:PAAF1 module followed by dissociation of PSMD5.
Synonyms: KIAA0072; S5B
Tractability: PROTAC: ubiquitination databases record sites on it; its protein half-life has been measured.
Gene: Protein-coding gene on chromosome 9 (120,815,496 to 120,842,984, reverse strand). Ensembl gene ENSG00000095261.
Subcellular location (Human Protein Atlas): Cytosol; Nucleoplasm; Basal body; Centrosome; Connecting piece; Mid piece
Pathways (Reactome):
Metabolism of proteins: Proteasome assembly
Gene Ontology:
Molecular function: protein binding
Biological process: proteasome regulatory particle assembly; proteasome assembly
Cellular component: proteasome regulatory particle, base subcomplex; cytosol; proteasome accessory complex; proteasome complex
Genetic constraint (gnomAD): Loss-of-function variants: 29 observed, 42.94 expected, observed/expected ratio (o/e) 0.68, 90% interval 0.5 to 0.92. The upper end of that interval is the gene's LOEUF score, 0.92, which puts it in group 3 of 6, group 1 being the genes least tolerant of losing a copy. Missense variants: 481 observed, 532.51 expected, observed/expected ratio (o/e) 0.9, 90% interval 0.84 to 0.97. Synonymous variants: 183 observed, 201.62 expected, observed/expected ratio (o/e) 0.91, 90% interval 0.8 to 1.03.
Homologues: Orthologues: chimpanzee PSMD5 (99% identical), macaque PSMD5 (99% identical), pig PSMD5 (94% identical), dog PSMD5 (92% identical), rabbit PSMD5 (92% identical), guinea pig PSMD5 (91% identical), mouse Psmd5 (90% identical), rat Psmd5 (89% identical), zebrafish psmd5 (58% identical), Drosophila melanogaster CG12096 (23% identical), Caenorhabditis elegans F35G12.12 (18% identical).
Diseases named in the same sentence as PSMD5 in open-access papers:
PSMD5 is named in the same sentence as 10 diseases in open-access papers, as found by Europe PMC text mining. Sharing a sentence is not in itself a finding about the gene and the disease. The quoted sentences say what the papers report.
multiple myeloma (3 papers, 2020 to 2021). "An example is that bortezomib, a reversible inhibitor of the chymotrypsin-like activity of PSMD5 in the proteasome, has been widely used in the treatment of multiple myeloma 23-24." (PMID 33046988, 2020).
colorectal tumor (2 papers, 2022 to 2023). "Inactivation of PSMD5 may play a significant role in colorectal tumors by the assembly of 26S proteasome." (PMID 35409691, 2022). "Inactivation of PSMD5 was shown to promote colorectal tumor progression, TNF-α increases PSMD5 expression through NFκB." (PMID 37349676, 2023).
esophageal cancer (1 paper, 2021). A primary or metastatic malignant neoplasm involving the esophagus. "Interestingly, other proteasome subunits were also expressed highly in EC and the elevated expression of PSMA2, PSMA5, PSMC6, PSMD5, PSMD10 indicated poor prognosis of EC patients respectively, which revealed a crucial role of 26S proteasome in esophageal cancer." (PMID 33897885, 2021).
glioma (1 paper, 2023). A benign or malignant brain and spinal cord tumor that arises from glial cells (astrocytes, oligodendrocytes, ependymal cells). "The mRNA levels of PSMD5/8/9/10/11/13/14 were higher in GBM than in normal brain tissues, and the mRNA levels of PSMD1/4/5/8/9/11/12 were higher in high‐grade glioma (WHO grade III & IV) than in low‐grade glioma (WHO grade II)." (PMID 37485655, 2023).
ocular coloboma (1 paper, 2022). "Specifically, mutations in the PSMD5 gene resulted in ocular coloboma and vertebral defects in zebrafish, suggesting an important role for PSMD5 during optic fissure closure and vertebral development." (PMID 34750284, 2022).
cancer (5 papers, 2010 to 2025). A tumor composed of atypical neoplastic, often pleomorphic cells that invade other tissues. "For example, the methylation regions located in ACAA2, NUSAP1, OGFOD1, PSMD5, SNRNP40, USP37 and XRCC6 are shared by five cancers (i.e., BRCA, CESC, COAD, KIRP and SARC)." (PMID 34464378, 2021).
PSMD5 also shares sentences with these, for which no sentence is quoted: astrocytomas (1 paper); ovarian serous carcinoma (1); schizophrenia (1); serous ovarian cancer (1).